VCX3B (variable charge X-linked 3B)
Description:
May mediate a process in spermatogenesis or may play a role in sex ratio distortion.
Synonyms: VCX-C; VCXC
Tractability: No criterion of Open Targets' tractability assessment is met for any kind of drug.
Gene: Protein-coding gene on chromosome X (8,464,830 to 8,466,510, forward strand). Ensembl gene ENSG00000205642.
Gene Ontology:
Biological process: brain development
Cellular component: nucleolus; nucleus
Homologues: Paralogues in human: VCX (78% identical), VCX3A (73% identical), VCX2 (50% identical), VCY (46% identical), VCY1B (46% identical).